POSTN (periostin)
Diseases named in the same sentence as POSTN in open-access papers (continued):
Sharing a sentence is not in itself a finding about the gene and the disease.
pancreatic cancer (50 papers, 2007 to 2025). "In the current study, we observed that higher POSTN expression is associated with a poorer prognosis in pancreatic cancer, leading to the infiltration of immune‐suppressive cells, especially M2 macrophages." (PMID 38389400, 2024). "To explore a potential association between POSTN expression and the immune landscape of pancreatic cancer, we first analyzed the TCGA cohort using the ESTIMATE algorithm." (PMID 38389400, 2024). "We observed that higher levels of POSTN were associated with shorter overall survival and recurrence‐free survival in pancreatic cancer patients." (PMID 38389400, 2024). "Taken together, POSTN expression was higher in pancreatic cancer patients and was associated with shorter OS and RFS." (PMID 38389400, 2024). "Lastly, we examined the tumor mutational burden (TMB) in pancreatic cancer in relation to POSTN expression." (PMID 38389400, 2024). "In the current study, we found that expression of POSTN is associated with shorter overall survival and recurrence‐free survival in pancreatic cancer patients." (PMID 38389400, 2024). "High periostin expression in tumor stroma is associated with decreased patient survival in pancreatic cancer and prostate cancer." (PMID 36224629, 2022). "An extracellular matrix protein implicated in pancreatic cancer called periostin was found to increase 8-fold in SCA cyst fluid compared to mucinous lesions." (PMID 35299739, 2022). "Periostin is considered as a subtype A biomarker and high expression of periostin is associated with shorter overall survival of pancreatic cancer patients." (PMID 33333727, 2020). "Taken together, higher POSTN expression is associated with higher stromal infiltration and enhanced immune suppression in the tumor microenvironment, and attenuates immunotherapy efficacy in pancreatic cancer patients." (PMID 38389400, 2024). "Furthermore, we observed that higher POSTN expression was associated with poor response to ICIs in pancreatic cancer patients." (PMID 38389400, 2024). "Taken together, our data suggest that higher POSTN expression is associated with higher stromal infiltration and enhanced immune‐suppressive condition in the tumor microenvironment, potentially attenuating immunotherapy efficacy in pancreatic cancer patients." (PMID 38389400, 2024). "High expression of POSTN is predicted to correlate with lower sensitivity to immunotherapy with checkpoint inhibitors in pancreatic cancer." (PMID 38389400, 2024). "Previous research has shown that periostin (POSTN) promotes pancreatic cancer cell proliferation, migration, and invasion." (PMID 38389400, 2024). "To further clarify the role of periostin in pancreatic cancer, we screened DEGs depending on POSTN expression levels." (PMID 38389400, 2024). "When compared with healthy pancreatic tissues, pancreatic cancer tissues displayed significantly higher levels of POSTN, which was indicative of a worse prognosis." (PMID 38389400, 2024). "According to median POSTN expression, we divided 178 pancreatic cancer samples into groups of POSTN‐high and POSTN‐low expression." (PMID 38389400, 2024). "The IPS was significantly higher in the POSTN‐low expression group (p = .001), suggesting that POSTN expression attenuates immunotherapy efficacy in pancreatic cancer patients." (PMID 38389400, 2024). "In the case of pancreatic cancer, it has been shown that POSTN is predominantly expressed and secreted by PSCs and CAFs." (PMID 38389400, 2024). "High POSTN expression is predicted to result in reduced sensitivity to immunotherapies involving checkpoint inhibitors in pancreatic cancer." (PMID 38389400, 2024).
pancreatic cancer (continued). "Pancreatic cancer patients with low POSTN expression showed a better (predicted) response to CTLA4 and/or PD1 and PD‐L1 checkpoint inhibitors." (PMID 38389400, 2024). "AGR2, POSTN, TFF1, and CP were selected because their transcribed proteins have been previously implicated as potential biomarkers for pancreatic cancer." (PMID 36812168, 2023). "Previous studies have shown that POSTN can inhibit the apoptosis of colon, liver, gastric, and pancreatic cancer cells, and promote tumor cell growth and metastasis." (PMID 37572219, 2023). "PDAC patients also presented with upregulated periostin expression, which has been linked to a shorter overall survival, and cystatin SN, which contributes to pancreatic cancer cell proliferation and may represent a potential biomarker for the early detection of pancreatic cancer." (PMID 37296850, 2023). "The overexpression of the periostin gene has been detected in various cancer types including pancreatic cancer." (PMID 36830807, 2023). "Our study shows for the first time that targeting periostin and thereby decreasing collagen density increases the infiltration and the cytotoxic activity of natural killer cells against pancreatic cancer cells and pancreatic stellate cells." (PMID 36830807, 2023). "In pancreatic cancer, periostin mRNA levels were shown to be 42 times higher than the normal pancreas and PSCs are the only source of periostin in the pancreas." (PMID 36830807, 2023). "ECM proteins, such as periostin, deposits around the capillaries of pancreatic cancer, and hypoxia increased periostin expression in PSCs." (PMID 35053572, 2022). "In vivo studies showed that reduced POSTN expression in pancreatic cancer cells inhibited tumor growth and significantly decreased VEGF expression in mice, which resulted in a decrease in the number of metastases and inhibited angiogenesis." (PMID 36077762, 2022). "We investigated the expression of TRPM7, TRPM6 and periostin (POSTN), a marker of activated CSPs, in pancreatic cancer samples using GEPIA tool." (PMID 35883700, 2022). "Some studies have found that inducing periostin expression in tumor cells can prevent apoptosis and increase survival under several stress conditions, as observed in pancreatic cancer cells." (PMID 36224629, 2022). "We investigated the expression of TRPM7, TRPM6 and POSTN in pancreatic cancer samples (PAAD-TCGA) and normal pancreas samples from GTEX using GEPIA2021, which enables to filter the cell types of interest in normal tissue from GTEX or cancer types from TCGA." (PMID 35883700, 2022). "In a hepatic metastasis model of pancreatic cancer, periostin was shown to be induced by granulin secreted from metastasis-associated macrophages (MAMs)." (PMID 33466303, 2021). "In pancreatic cancer, periostin has been detected in cancer epithelial cells, pancreatic stellate cells, and tumor stroma." (PMID 33466303, 2021). "Our study demonstrated that interaction between fibroblasts and cancer cells is important for the secretion of periostin from fibroblasts, which is compatible with reports for pancreatic cancer and renal cell carcinoma." (PMID 30131847, 2018). "To date, there are few studies on the relationship between periostin and pancreatic cancer, and the biological role of periostin has yet to be determined." (PMID 29163770, 2017). "Semiquantitative analysis showed an increased intensity of periostin staining in pancreatic cancer compared with normal tissues." (PMID 29163770, 2017). "We performed immunohistochemical staining for periostin on a large cohort of primary pancreatic cancer patients (n = 100)." (PMID 29163770, 2017). "To determine the significance of periostin in pancreatic cancer, we first analyzed the expression level of periostin in PCCs and PSCs by real-time RT-PCR, western blot analysis, and ELISA." (PMID 29163770, 2017).
pancreatic cancer (continued). "Together, our results suggest that periostin regulates the activity of pancreatic cancer cells through EGFR-Akt and EGFR-Erk-c-Myc signaling pathways." (PMID 29163770, 2017). "Tissue microarray immunohistochemical assays including 80 pancreatic cancer tissues and paired normal tissues were used to understand the function relationship between periostin expression and PDAC pathologic stage and overall survival." (PMID 29163770, 2017). "To further investigate the correlation between periostin expression and pancreatic cancer progression, we used TMAs to study periostin expression levels in pancreatic cancer and corresponding paired normal tissues." (PMID 29163770, 2017). "To verify the role of periostin in pancreatic cancer progression in vivo, we performed xenograft tumor assays by subcutaneous co-injection of SW1990 cells and PSC cells that were stably transfected with periostin-shRNA 1 lentivirus." (PMID 29163770, 2017). "We also observed a significant decrease in proliferation, metastasis, and clonality of pancreatic cancer cells when co-cultured with supernatant of periostin shRNA-transfected PSCs." (PMID 29163770, 2017). "Numerous studies showed an up-regulation of both POSTN protein and mRNA levels in a plethora of different tumours, including glioblastoma, neuroblastoma, breast, colon and pancreatic cancer." (PMID 26930720, 2016). "Periostin acts as a ligand of the β4-integrin receptor on pancreatic cancer cells and activates downstream AKT and MAPK pathways." (PMID 24213498, 2012). "The secretory protein periostin (osteoblast-specific factor 2) is strongly expressed in pancreatic cancer." (PMID 24281218, 2010). "In pancreatic cancer cells, periostin was shown to bind to α6β4 integrin, thereby promoting phosphorylation of focal adhesion kinase and PKB through activation of the PI3 kinase pathway." (PMID 18086302, 2007). "We detected a 72-fold increase of POSTN transcription in pancreatic adenocarcinoma compared to normal tissues (P = 0.06), in line with previous studies reporting a 42- to more than 100-fold increase of POSTN mRNA level in pancreatic tumors." (PMID 18086302, 2007). "The results showed that TAFA2 and POSTN were significantly elevated in IR-resistant pancreatic cancer cells, suggesting that TAFA2 may play an important role in radiotherapy resistance of pancreatic cancer." (PMID 40103813, 2025). "In addition, a significant positive correlation was found between high POSTN expression in pancreatic cancer and VEGF levels, which suggests an essential role of POSTN in the mechanisms regulating angiogenesis and metastasis development." (PMID 39272978, 2024). "In addition, one in vivo study showed that decreasing POSTN levels in pancreatic cancer cells inhibited tumor growth, reduced VEGF expression, and reduced angiogenesis and metastasis in mouse models." (PMID 39272978, 2024). "In this study, the local promotion function of UTMD technology was combined with drug and gene-loaded nanoparticles, which significantly improved the delivery efficiency of gemcitabine and periostin silencing, as well as the therapeutic effect against pancreatic cancer." (PMID 38706910, 2024). "To determine whether expression of POSTN is higher predominantly in basal‐like subtype, we first obtained TCGA pancreatic cancer data via the HPA database, which included survival information for 176 individual patients." (PMID 38389400, 2024). "Previous studies have demonstrated that POSTN expression levels may promote pancreatic cancer proliferation, migration, and invasion." (PMID 38389400, 2024). "Previous research has shown that POSTN expression levels may promote pancreatic cancer cell proliferation, migration, and invasion." (PMID 38389400, 2024). "Our study highlighted the significant role of stromal POSTN expression in pancreatic cancer." (PMID 38389400, 2024).
pancreatic cancer (continued). "We and others have previously shown that periostin (Postn) promotes pancreatic cancer metastasis by supporting the outgrowth of disseminated cancer cells, and our prior results confirmed that pSTAT3+myMAFs promoted anchorage-independent outgrowth of cancer cells in vitro." (PMID 38678021, 2024). "POSTN expression and clinicopathological features of pancreatic cancer patients." (PMID 38389400, 2024). "Our findings suggest that targeting POSTN could potentially reprogram the immunosuppressive tumor microenvironment and enhance the efficacy of immunotherapy in pancreatic cancer." (PMID 38389400, 2024). "Our findings further assist in elucidating the role of POSTN in pancreatic cancer and POSTN may be a potential target to reprogram the immunosuppressive tumor microenvironment for pancreatic cancer immunotherapy." (PMID 38389400, 2024). "However, the relationship between POSTN expression, immune cell infiltration, and the efficacy of immunotherapy in pancreatic cancer is unclear." (PMID 38389400, 2024). "Therefore, we aimed to further clarify the relationship between periostin, pancreatic cancer cells, and PSCs, and to explore the molecular functions of periostin." (PMID 37444482, 2023). "The high tumor mRNA expression of POSTN was associated with a significantly worse overall survival (all-time risk of death: HR = 2.3 and 3.8 for patients from the TCGA and CPTAC programs, respectively) of pancreatic cancer patients." (PMID 37444482, 2023). "These authors suggested that POSTN promoted angiogenesis in pancreatic cancer by activating the Erk/VEGF signaling and it could become a therapeutic target in this cancer." (PMID 36077762, 2022). "The current review study identifies 22 IHC biomarkers as diagnostic tools for pancreatic cancer that embrace: Pentraxin-3, ENO1, REG4, POSTN, CA125, CA242, Galectin-1, Galectin-9, Maspin, pVHL, MUC1, MUC5AC, THBS2, LTBP2, CPA4, IMP3, CD13, Dkk1, KOC, S100P, Mesothelin, PAM4." (PMID 34988027, 2021). "Periostin expression was positively correlated with the clinical stage of pancreatic cancer." (PMID 29163770, 2017). "Together, our findings provide novel insights into the role of microenvironmental periostin in pancreatic cancer progression, and periostin may serve as a prognostic biomarker for PDAC." (PMID 29163770, 2017). "To better understand the molecular mechanism by which periostin promotes pancreatic cancer progression, we examined several signaling transduction pathways that might be critical in tumorigenesis and regulated by periostin." (PMID 29163770, 2017). "In pancreatic cancer cells, the α6β4-integrin complex acts as the cell receptor of periostin, and this interaction promotes migration through phosphorylation of focal adhesion kinase (FAK) and protein kinase B (AKT) through activation of the PI3 kinase pathway." (PMID 24273600, 2013). "The data on the function of periostin in pancreatic cancer are unclear and conflicting." (PMID 24281218, 2010). "The expression of periostin is elevated in certain pathological circumstances, such as inflammatory conditions, and periostin is frequently overexpressed in the tumor stroma of some types of carcinomas, including prostate cancer, lung cancer, colorectal cancer, and pancreatic cancer." (PMID 39941916, 2025). "We next analyzed the Kaplan–Meier plotter database, which revealed that high expression of POSTN was associated with shorter overall (OS) (HR = 1.69, 95% CI: 1.03–2.78, p = .038) as well as relapse‐free survival (RFS) (HR = 4.72, 95% CI: 1.37–16.18, p = .0071) in pancreatic cancer patients." (PMID 38389400, 2024). "POSTN is related to pancreatic cancer prognosis, and may influence immune cell infiltration." (PMID 38389400, 2024).
pancreatic cancer (continued). "The protein products from AGR2, CEAMAN6, GNMT, PDIA2, POSTN, RBPJL and S100P have been reported as potential diagnostic and prognostic biomarkers for pancreatic cancer or have demonstrated to be involved in either pancreatic cancer, initiation, migration, invasion, metastasis, or chemoresistance." (PMID 36812168, 2023). "Moreover, periostin promoted abdominal cavity metastasis of pancreatic cancer cells in nude mice." (PMID 29163770, 2017). "To assess the role of POSTN in tumorigenicity of pancreatic cancer cells in vivo, we established a subcutaneous cell-derived xenograft (CDX) model by co-injecting BxPC-3 cells with CAF-NC or CAF-POSTN into BALB/c-Nude mice." (PMID 40520021, 2025). "Evaluation of POSTN expression indicated low levels in pancreatic cancer cell lines but markedly higher levels in primary CAFs; and CCC-HPE-2 cells exhibited lower POSTN expression." (PMID 40520021, 2025). "Hence, it needs to be further clarified in the future whether POSTN‐positive CAFs activate signaling pathways in pancreatic cancer cells to induce infiltration and differentiation of macrophages, or POSTN‐positive pancreatic CAFs directly recruit monocyte/macrophages and support differentiation." (PMID 38389400, 2024). "The levels of POSTN and TNC increase in tumors such as breast, lung, and pancreas carcinomas, where they interact with other ECM molecules to promote cancer cell survival, invasion, and metastatic spreading." (PMID 39201614, 2024). "At 150 ng/ml, periostin can prevent EMT and decrease in vitro cell migration in pancreatic cancer cells, leading to metastatic suppression in vivo." (PMID 36224629, 2022). "In this study, periostin (POSTN) was discovered to increase LINC01133 via the epidermal growth factor receptor (EGFR)/MYC axis and promote exosome secretion in pancreatic cancer cells." (PMID 35055115, 2022). "Periostin modulates EMT and promotes migration and metastasis via the AKT signaling pathway in pancreatic cancer cells in a dose-dependent manner." (PMID 36224629, 2022). "Analyzed IHC biomarkers that can differentiate pancreatic cancer from chronic pancreatitis encompass REG4, POSTN, CA242, Galectin-1, maspin, pVHL, IMP3, CD13, and PAM4." (PMID 34988027, 2021). "Abnormally high expression levels of periostin can increase α-SMA, periostin, collagen-1, fibronectin and TGFβ expression in PSCs and can promote growth, resistance to starvation, and invasion of pancreatic cancer cells." (PMID 30060755, 2018). "Genes (n = 10) in cluster 2 were entirely labeled as activated stroma, containing periostin (POSTN), fibronectin 1 (FN1) and collagens (COL10A1, COL11A1), which have already been identified as deregulated in precursor lesions of pancreatic cancer." (PMID 29675033, 2018). "Other reports suggest that periostin supports growth in gastric cancer cells through ERK activation, and that ERK signaling occurs downstream of periostin in lung cancer and pancreatic cancer." (PMID 30131847, 2018). "Through activation by pancreatic cancer cells, PCS also secrete the ECM component periostin into the tumor micro-environment." (PMID 24213498, 2012). "We observed strong stromal POSTN staining in pancreatic cancer tissues (UKH) but not in normal samples." (PMID 38389400, 2024). "Although there are no clinical trials targeting periostin currently, some ongoing or completed clinical trials exist focusing on pancreatic cancer stroma." (PMID 36830807, 2023). "First, the interactions between CTHRC1 and periostin likely occurs exclusively in PSCs, not in pancreatic cancer cells." (PMID 37444482, 2023). "Periostin was not secreted by any of the four pancreatic cancer cell lines (MIA PaCa-2, PANC-1, CFPAC-1, and BxPC-3) with or without treatment with CTHRC1 (10, 100, or 1000 ng/mL)." (PMID 37444482, 2023).